ALPL (alkaline phosphatase, biomineralization associated)
Diseases named in the same sentence as ALPL in open-access papers (continued):
Sharing a sentence is not in itself a finding about the gene and the disease.
tumor (27 papers, 2012 to 2025). "At the cellular level, higher ALPL expression is inversely related to tumor aggressiveness; OS cells with high ALPL activity show reduced invasiveness and metastatic potential, likely due to upregulation of cell adhesion genes (e.g., CDH13, CAV1)." (PMID 41154810, 2025). "DAC treatment led to enhanced differentiation as demonstrated by increased ALPL expression, and suppressed tumor growth in vitro and in vivo." (PMID 38946977, 2024). "A separate qPCR analysis of 36 fresh LUAD samples and matched healthy tissues revealed significantly lower ALPL expression in tumor tissues, consistent with the results obtained using the TCGA database." (PMID 33858415, 2021). "In men with PCa, tumour-derived ALPL correlated with EMT markers, and high ALPL expression was associated with a significant reduction in disease-free survival." (PMID 28006818, 2017). "A reduction in tumour-derived ALPL expression or ALP activity increased cell death, mesenchymal-to-epithelial transition and reduced migration." (PMID 28006818, 2017). "The higher number of seeding locations (≥ 3) showed the downregulation of PTGDS in the tumor (log2FC = − 0.42, adjusted p-value < 0.001) and stromal regions (log2FC = − 0.31, adjusted p-value < 0.001) and ALPL in the tumor region (log2FC = − 0.48, adjusted p-value < 0.001)." (PMID 39135097, 2024). "ALPL also plays very different roles in different tumor types." (PMID 33858415, 2021). "As expected, NB5t primary cells showed increased expression of mesenchymal genes (NT5E, ENG, ACTA2, MME, CD44, VIM or ALPL), while NB5t tumor sample expressed mostly neuronal genes (TH, ENO2, NCAM1, DDC or CHGB) reflecting the neuroblastic phenotype of stage 4/M NB tumors." (PMID 29163787, 2017). "Furthermore, ALPL, the gene encoding tissue-nonspecific alkaline phosphatase, is highly expressed in OS cells, highlighting its essential role in bone mineralization and its relevance in tumor biology." (PMID 41154810, 2025). "In the tumor microenvironment, CD10+ALPL+ neutrophils can exhibit strong immunosuppressive activity and induce obvious “irreversible” depletion of T cells." (PMID 40566633, 2025). "OstCAFs expressed numerous genes similar to OS cells (ALPL, RUNX2), with GSVA linking them to TGF_BETA_SIGNALING_PATHWAY, PATHWAYS_IN_CANCER, and WNT_SIGNALING_PATHWAY, highlighting their involvement in tumor progression." (PMID 38755647, 2024). "TMX4, ALPL, PTX3, BHLHE40, TNFRSF12A and CST3 demonstrated significant overexpression in LUSC tumour tissues, whereas CLDN1, VKORC1 and ADD3 exhibited significant underexpression in the HPA database." (PMID 38520221, 2024). "Mechanically, tumour cells secreted NAMPT, which reprogrammed CD10 + ALPL+neutrophils via NTRK1, keeping them immature and preventing their maturation and activation." (PMID 39144662, 2024). "Taken together, our study further correlates ALPL and RUNX2 signaling with the molecular signaling of RANKL and MMP, a modulation that affects the tumor cell invasiveness and phenotypic plasticity." (PMID 38435029, 2023). "Of course, future studies will be required to better explain these results and to clarify the mechanistic functions of ALPL, GPR68, NETO1, and VGF in the GBM TME and how they can mediate the success of CW application in the tumor resection cavity." (PMID 35884475, 2022). "ALPL, APOL6, SON, and VWF proteins were significantly differentially expressed between normal and tumor tissues." (PMID 35991564, 2022). "The results revealed low expression of ALPL, RUNX2, and CLEC11A in PC, while highly expressed in PT and MLN (all p < 0.05, Wilcoxon test), which suggested abnormal activation and malignant transformation of OB cells during tumor progression." (PMID 38755647, 2024). "Notably, TMX4, ALPL, PTX3, BHLHE40, TNFRSF12A and CST3 demonstrated significant overexpression in LUSC tumour tissues, whereas CLDN1, VKORC1 and ADD3 exhibited significant underexpression." (PMID 38520221, 2024).
tumor (continued). "In particular, ALPL, APOL6, SON, and VWF were lowly expressed in tumor tissues." (PMID 35991564, 2022). "For the castration-induced regression nadir group (i.e., those with the weakest or most unsuccessful castration-induced tumor regression), GSE1, CYP3A5, CTNNB1, CYP3A4, POU5F1, ABCB1, alkaline phosphatase liver/bone/kidney isozyme (ALPL), PROM1/CD133, ABCG2, and SOX2 were concomitantly upregulated." (PMID 34439112, 2021). "We have identified that PCa cells express ALPL, the gene that encodes for tissue nonspecific ALP, and hypothesised that tumour-derived ALPL may contribute to disease progression." (PMID 28006818, 2017). "These include some of the tumor associated proteins with differential levels in both stage IIIA and IVB such as alkaline phosphatase, tissue-nonspecific isozyme isoform 1 preproprotein (ALPL), dipeptidyl peptidase 4 isoform X1 (DPP4), protein TFG isoform X2 (TFG)." (PMID 34876625, 2021).
genetic disease (25 papers, 2019 to 2025). "HPP is a genetic disorder caused by a mutation in the ALPL gene, impairing the function of TNSALP." (PMID 41179594, 2025). "Conversely, in rare genetic disorders such as HPP, skeletal fragility stems from an inherited enzyme deficiency—specifically, insufficient activity of TNSALP, encoded by the ALPL gene." (PMID 41517371, 2025). "Although the absolute number of patients with mutation in the ALPL gene identified in the entire study population is relatively low, it should be noted that HPP is a rare genetic disease with a low prevalence of 1/6370 for mild HPP." (PMID 36514157, 2022). "HPP is a genetic disorder caused by a mutation in the ALPL gene, impairing the function of the tissue‐nonspecific isoenzyme of alkaline phosphatase (TNSALP)." (PMID 41179594, 2025).
cancer (14 papers, 2019 to 2025). A tumor composed of atypical neoplastic, often pleomorphic cells that invade other tissues. "ALPL is present at high levels in bone, liver, kidney, brain, skin, and vascular endothelial cells, which are typical locations of cancer metastasis and sites of ectopic calcification." (PMID 32650435, 2020). "We therefore concluded that ALPL downregulation in LUAD might be an important molecular event for cancer development or progression." (PMID 33858415, 2021). "According to recent reports, ALPL also plays a role in cancer." (PMID 33858415, 2021). "Thus, the ability of ALPL to down-regulate c-Myc may represent a novel approach to cancer treatment." (PMID 33858415, 2021). "Therefore, the function of ALPL in cancer and the related mechanisms remain controversial." (PMID 33858415, 2021). "Expression of ALDH1A1, ALPL, ITGA6, CD44, PROM1 (CD133), LGR5, and YAP1 upregulated in the E2 and E3 phenotypes was consistent with cancer hallmarks including cell plasticity, self-renewal, and drug-tolerant persistence." (PMID 38915538, 2024). "In this study, we show for the first time that ALPL inhibits the metastasis of LUAD cells via the p-ERK1/2-c-Myc-RhoA axis, which extends our understanding of the role of ALPL in cancer development." (PMID 33858415, 2021). "At the same time, pan-cancer analysis also shows that PPM1A, DAPK1, FBP1, PYHIN1, ALPL and SMCHD1 have significant amplification in PCa." (PMID 30867653, 2019). "The essential function of ALPL/TNAP in mitochondria have recently been intensively studied and imply function in adaptive thermogenesis of fat cells and in regulation of ATP levels in bone, muscle progenitor, and cancer cells." (PMID 40530336, 2025).
bone disorder (9 papers, 2011 to 2026). "In the present study, we recognize a novel genetic skeletal disease in dogs and identify a homozygous missense change in the ALPL gene." (PMID 30700765, 2019).
infection (4 papers, 2022 to 2025). The state of being infected such as from the introduction of a foreign agent such as serum, vaccine, antigenic substance or organism. "Six months after infection, the concentration of bone-tissue metabolism markers remained multidirectional: a low concentration of ALPL was accompanied with a high concentration of RANKL." (PMID 37626725, 2023). "Blood samples were drawn in RNA preservative (Tempus) and whole blood RNA was analyzed by droplet digital PCR (ddPCR) for RNA transcripts related to neutrophil response to infection by bacterial (DEFA1; ALPL, IL8RB/CXCR2), and viral (IFI27, RSAD2) pathogens." (PMID 41385588, 2025). "When ALPL + IL8RB > 20% was combined with a DEFA1 > 10%, the positive predictive value became more pronounced for the outcomes of likely infection (0.90), surgery (0.86) and hospital admission (0.83)." (PMID 36759691, 2023). "By day 18 post-infection, a statistically significant decrease in RANKL concentration, accompanied by a tendency to decrease ALPL level, was observed in all groups as compared to the initial values." (PMID 37626725, 2023). "When analyzed using a pre-established threshold, ALPL + IL8RB > 20%, the biomarker identified infection, need for surgery and hospital admission with positive likelihood ratios of 4.25, 3.97, 2.80 and negative likelihood ratios of 0.30, 0.70, 0.45, respectively." (PMID 36759691, 2023). "Six months after infection in group 2, a high concentration of non-specific alkaline phosphatase (ALPL) and high activity of total ADA and ADA-1 were preserved." (PMID 37626725, 2023). "Four months after infection in group 2, along with preservation of high activity of total ADA and ADA-1, the concentration of nonspecific alkaline phosphatase (ALPL) was also found to increase." (PMID 37626725, 2023).
cardiovascular disease (3 papers, 2021 to 2022). "ALPL has the potential to be a new predictor of cardiovascular disease-related morbidity and mortality." (PMID 35755167, 2022).
heart disease (3 papers, 2019 to 2021). "In summary, exosomal ALPL and CXCR2 have the predictive potential to provide greater accuracy and identification of cardiac disease." (PMID 34490374, 2021).
connective tissue disorder (2 papers, 2024 to 2026). A disease involving the connective tissue. "Analysis of genes causing connective tissue disorders according to ACGS guidelines revealed four P/LP variants in COL1A1, COL6A1, FKBP14, and ALPL." (PMID 39298385, 2024).
ALPL also shares sentences with these, for which no sentence is quoted: metabolic disorder (22 papers); metabolic bone disorder (7); epilepsy (5); Myocardial fibrosis (4); ankylosis (3); Hypercalciuria (3); Osteopenia (3); autoimmune disease (2); bone mineral disorders (2); calcification (2); Cleidocranial Dysplasia (2); coronary artery disease (2); depression (2); hemochromatosis (2); infantile hypophosphatasia (2); nephrocalcinosis (2); neurological diseases (2); pancreatic carcinoma (2); Pseudoxanthoma elasticum (2); Seizure (2); skeletal dysplasia (2); steatosis (2); tendinitis (2); acute kidney injury (1); acute myocardial infarction (1); anemia (1); ankylosing spondylitis (1); Anxiety (1); aortic stenosis (1); Apert syndrome (1).
A further 72 diseases each share a sentence with ALPL in 1 paper.